EVA1A (eva-1 homolog A, regulator of programmed cell death)
Diseases named in the same sentence as EVA1A in open-access papers (continued):
Sharing a sentence is not in itself a finding about the gene and the disease.
thyroid cancer (1 paper, 2020). "Results showed that Eva‐1 homolog A (EVA1A) may be a potential gene for the PTC‐associated gene in thyroid cancer." (PMID 32969138, 2020). "In this study, the expression of EVA1A in 43 thyroid cancer tissues and paired normal tissues was detected using the quantitative real‐time PCR (qRT‐PCR) to verify the results of transcriptome sequencing." (PMID 32969138, 2020). "This work aimed to determine the relationship between EVA1A expression and its role in the proliferation, metastasis and apoptosis of thyroid carcinoma." (PMID 32969138, 2020). "In this work, the role of EVA1A expression in thyroid cancer was investigated." (PMID 32969138, 2020). "However, the relationship between EVA1A and thyroid cancer remains poorly understood." (PMID 32969138, 2020). "However, the molecular mechanisms of EVA1A in thyroid carcinoma are still unclear." (PMID 32969138, 2020). "Real‐time PCR was performed to detect the expression level of EVA1A in 43 pairs of PTC and four thyroid cancer cell lines." (PMID 32969138, 2020).
cancer (15 papers, 2015 to 2026). A tumor composed of atypical neoplastic, often pleomorphic cells that invade other tissues. "EVA1A overexpression can significantly reduce the cancer-promoting effects caused by miR-103a-3p mimics." (PMID 36273122, 2022). "The expression of EVA1A was analyzed using the GEPIA database(GEPIA (cancer-pku.cn)), which is publicly accessible." (PMID 38529374, 2024). "The evidence indicates that the expression of EVA1A is cell type-specific and tissue type-specific, and is substantially reduced in cancer tissues." (PMID 35743108, 2022). "EVA1A (Eva-1 homolog A), a novel protein involved in autophagy and apoptosis, functions as a tumor suppressor in some human primary cancers, including hepatocellular carcinoma (HCC)." (PMID 36273122, 2022). "It has been reported that EVA1A significantly induces the caspase-3-mediated apoptosis of cancer cells to inhibit cancer." (PMID 35743108, 2022). "EVA1A upregulation attenuates the cancer-promoting effects of miR-103a-3p, and EVA1A downregulation greatly reduces cell apoptosis induced by miR-103a-3p inhibition." (PMID 36273122, 2022). "It is believed that with the deepening of research, EVA1A will provide a new strategy for cancer treatment." (PMID 35743108, 2022). "Autophagy and apoptosis have been reported to be related with cancer, so the interplay between autophagy and apoptosis induced by EVA1A in GBM needs to be elucidated." (PMID 34201121, 2021). "Furthermore, some of the existing studies on the role of EVA1A in cancer only used in vitro experiments, so the results are relatively vulnerable and need to be further verified by in vivo experiments in the future." (PMID 35743108, 2022). "Therefore, in this review, we review the recent progress in delineating the role of EVA1A in different kinds of cancers, and analyze the related mechanisms, hoping to provide a theoretical reference for in-depth research in the future." (PMID 35743108, 2022). "However, the related mechanism, especially the role of EVA1A in cancers, has not been fully understood." (PMID 35743108, 2022). "EVA1A sometimes promotes the development of cancer, and sometimes the contrary." (PMID 35743108, 2022). "More and more studies have revealed that EVA1A plays a vital role in cancers, indicating that EVA1A may provide a new strategy for the treatment of cancers." (PMID 35743108, 2022). "However, the expression of EVA1A is low in several human cancers, including esophageal and gastric cancer." (PMID 35743108, 2022). "The expression of EVA1A is cell and tissue specific and is notably decreased in cancer." (PMID 34201121, 2021). "The restoration of EVA1A levels in some cancer cell lines is capable of inducing cell death by autophagy and apoptosis-related mechanisms, so inhibition of autophagy and apoptosis could reduce EVA1A-induced cell death 40-42." (PMID 32724459, 2020). "Eva-1 homolog A (EVA1A), also known as transmembrane protein 166 (TMEM166) and regulator of programmed cell death, is an endoplasmic reticulum associated protein, which can play an important role in many diseases, including a variety of cancers, by regulating autophagy/apoptosis." (PMID 35743108, 2022). "Therefore, we look forward to characterizing the link (if any) between EVA1A and Atg4B, and whether flubendazole could regulate both of these factors to further affect autophagy in cancer." (PMID 32724459, 2020). "Moreover, considering EVA1A acts as an adaptor protein to recruit or bind proteins in the lysosome or endoplasmic reticulum, we believe that with the deepening of the research, there may be other mechanisms related to the anti-cancer effects of EVA1A and deserve better clarification." (PMID 35440104, 2022). "Overexpression of EVA1A significantly attenuated the cancer-promoting effects of miR-103a-3p in HCC cells, while knockdown of EVA1A alleviated the mitochondrial dysfunction and apoptosis caused by miR-103a-3p inhibition." (PMID 36273122, 2022).
cancer (continued). "In this study, we investigated the role of flubendazole-induced mitophagy in mitochondrial function and anti-cancer effects and elucidated the mechanism of DRP1-mediated mitophagy via targeting EVA1A." (PMID 35440104, 2022). "Although previous studies have shown that EVA1A regulates autophagy through ATG5 and mTOR/RPS6KB1 pathways in cancer, the mechanism of EVA1A regulating autophagy in cancer is not completely clear and needs to be further clarified." (PMID 35743108, 2022). "We previously reported that flubendazole could restore the expression of EVA1A in TNBC cells, therefore inducing autophagic cell death and eliciting anti-cancer effects." (PMID 35440104, 2022).
tumor (14 papers, 2016 to 2025). "High EVA1A expression was associated with age, pathological M stage, total tumor stage, and Carbohydrate antigen CA19-9 (CA19-9)." (PMID 38529374, 2024). "The logistic regression analysis of the TCGA data set indicated that the expression of EVA1A was an independent risk factor for tumour, nde and metastasis (TNM) in PTC." (PMID 32969138, 2020). "This disparity is statistically significant (P< 0.05), thereby suggesting a positive correlation between EVA1A expression levels and the extent of tumor invasion." (PMID 38529374, 2024). "Subsequently, the protein expression of EVA1A was examined in tumor tissues (n=90) and normal tissues (n=90) via immunohistochemistry staining conducted at our institution." (PMID 38529374, 2024). "In conclusion, we found increased EVA1A expression in CRC tissues, closely associated with patient age, tumor metastasis and stage, and the CA199 marker." (PMID 38529374, 2024). "The expression of EVA1A was decreased in tumor tissues of TNBC, which was reversed by FLU in vivo and in vitro." (PMID 35008943, 2022). "Recently, the downregulation of EVA1A and its tumor suppressor activity was shown to be a high profile." (PMID 36273122, 2022). "EVA1A has recently been reported to have antitumor activity in several carcinomas and is considered a tumor suppressor gene." (PMID 36273122, 2022). "Taken together, these results suggest that EVA1A is a bona fide target of miR-103a-3p and that its downregulation is involved in the tumor-promoting action of miR-103a-3p in HCC." (PMID 36273122, 2022). "In this study, we show for the first time that the tumor suppressive activity of EVA1A in HCC cells can be inhibited by miR-103a-3p." (PMID 36273122, 2022). "EVA1A expression was decreased in tumor tissues of TNBC and increased in flubendazole-treated TNBC in vivo and in vitro." (PMID 34201121, 2021). "Collectively, flubendazole induced autophagy-mediated death of TNBC cells by targeting EVA1A, thus inhibiting tumor proliferation and migration." (PMID 34201121, 2021). "In order to study the pathogenesis of PTC, Bang-Yi Lin and colleagues committed a series of experiments and found that the EVA1A expression level in tumor tissues of 43 patients with PTC was significantly higher than that in adjacent normal tissues." (PMID 34201121, 2021). "The expression level of EVA1A in tumour tissues was significantly higher compared with that in adjacent normal tissues." (PMID 32969138, 2020). "In brief, flubendazole can regulate autophagy and apoptosis by targeting EVA1A, further affecting tumor proliferation and migration." (PMID 32724459, 2020). "In summary, we first found that EVA1A in PTC was a potent oncogene of enhanced tumour aggressiveness." (PMID 32969138, 2020). "Adenovirus-mediated expression of EVA1A in various tumor cell lines promoted autophagy via inhibition of mTOR and induced apoptosis via activation of caspase-3, inhibiting tumor cell growth." (PMID 29749374, 2018). "The results showed that miR-125b suppressed tumor growth, whereas concomitant overexpression of EVA1A reversed the effect of miR-125b, restoring tumor size to control levels after oxaliplatin treatment." (PMID 29749374, 2018). "Another study showed that CCAAT/enhancer binding protein alpha is up-regulated in a portion of HCC patients and may promote lipid decomposition through EVA1A, providing energy for tumor cell survival." (PMID 41306774, 2025). "Recent studies have revealed that EVA1A expression is upregulated in liver and thyroid cancers, which might encourage tumor cell invasion and proliferation and result in a poor prognosis." (PMID 38529374, 2024). "The study suggests that EVA1A is increased in CRC tumor tissues and may serve as a potential biomarker for poor prognosis in CRC." (PMID 38529374, 2024). "Additionally, there was a higher expression of Eva1a mRNA in CRC tumor tissues than in normal tissues (P< 0.05)." (PMID 38529374, 2024).
tumor (continued). "Our study adds weight to the notion that EVA1A functions as a tumor suppressor in hepatocytes." (PMID 36273122, 2022). "Collectively, FLU could promote autophagic cell death of TNBC cells by promoting EVA1A, thus suppressing tumor proliferation and migration." (PMID 35008943, 2022). "Moreover, we demonstrated that excessive DRP1-mediated mitophagy is characterized as a critical event in response to the anti-tumor effects of EVA1A." (PMID 35440104, 2022). "Studies have shown that EVA1A is expressed in a cell-type-specific and tissue-type-specific manner, and compared with normal tissues, the expression of EVA1A is widely downregulated in tumor tissues." (PMID 36273122, 2022). "Similarly, the enhancing of the EVA1A-regulated autophagy can directly promote the growth of tumor cells." (PMID 34201121, 2021). "Accumulating evidence has revealed that EVA1A is a prominent tumor suppressor molecule." (PMID 32724459, 2020). "Additionally, an excess of EVA1A seems to promote tumor progression." (PMID 38529374, 2024). "Taken together, these results indicated that EVA1A reversed the tumor-inhibiting effect of miR-125b in xenograft tumors from oxaliplatin-resistant cells and promoted metastasis, confirming that miR-125b plays a role in preventing oxaliplatin resistance by downregulating its target EVA1A." (PMID 29749374, 2018). "Our previous studies identified EVA1A, which is consistently down-regulated in the hepatic tissues of HCC patients, as a tumor suppressor in HCC." (PMID 41306774, 2025). "Summarily, EVA1A induced autophagic death of TNBC cells, resulting in suppressing the tumor proliferation and migration to improve TNBC." (PMID 35743108, 2022). "Results showed that a low EVA1A expression was related to TNM stage (P = 0.032), tumor size (P = 0.0161), lymph node metastasis (P = 0.0168) and distant metastasis (P = 0.0185)." (PMID 36273122, 2022). "Upon silencing of EVA1A expression, the ability of flubendazole to induce autophagy and apoptosis was weakened in TNBC cells, while the tumor survival rate and MMP-2 levels were elevated." (PMID 32724459, 2020). "Among these genes, it has been reported that EVA1A and HAP1 expression is decreased in tumor tissues, while HIF1α is dramatically increased 36-38." (PMID 32724459, 2020). "The results of this study support the established hypothesis that the high expression of EVA1A in CRC tissues is significantly correlated with the M stage and overall stage of the tumor, with a statistically significant difference (P< 0.05)." (PMID 38529374, 2024). "Notably, the patient’s chronological age, the pathological M stage, the aggregate tumor stage, and the CA199 marker were significantly intertwined with EVA1A expression (P< 0.05)." (PMID 38529374, 2024). "We collected 25 pairs of HCC tumor tissues and the corresponding adjacent noncancerous tissues and determined the expression of EVA1A by immunohistochemical staining, RT‒qPCR and western blotting." (PMID 36273122, 2022). "EVA1A (Eva-1 homolog A), also known as TMEM166 (transmembrane protein 166) or FAM176A (sequence similarity 176 families), is a vacuole-located type I membrane protein, and its expression is typically diminished in a variety of tumor cells 39-45." (PMID 32724459, 2020).
heart disease (1 paper, 2017). "The results of our study suggested that Eva1a may be a promising therapeutic candidate for heart disease." (PMID 28151473, 2017).
infection (1 paper, 2025). The state of being infected such as from the introduction of a foreign agent such as serum, vaccine, antigenic substance or organism. "Other genes, such as EVA1A, which is involved in the regulation of autophagy and apoptosis, and ECE1 and Rab27b, which are associated with the growth, invasion, and metastasis of a variety of tumors, were also overexpressed in the context of vPdR-H30K-5U infection." (PMID 40006915, 2025).
liver (1 paper, 2022). "The previous studies have shown that EVA1A suppresses NLRP3 activation to improve liver ischemia-reperfusion injury through induction of autophagy in Kupffer cells." (PMID 35743108, 2022).
EVA1A also shares sentences with these, for which no sentence is quoted: Cerebral ischemia (2 papers); pituitary adenoma (2); adrenal cortical carcinoma (1); Autoimmunity (1); cardiomyopathy (1); cardiovascular disease (1); cerebral infarct (1); cervical cancer (1); esophagus cancer (1); gastric adenocarcinoma (1); gastric cancer (1); Hepatic failure (1); Insulin resistance (1); ischemic stroke (1); lung carcinoma (1); Mediterranean fever (1); metastasis (1); neuroblastoma (1); Obesity (1); parathyroid adenoma (1); pulmonary oedema (1); Stroke (1).